CD4 (CD4 molecule)
Diseases named in the same sentence as CD4 in open-access papers (continued):
Sharing a sentence is not in itself a finding about the gene and the disease.
lymphopenia (continued). "Lymphopenia, particularly the low frequency of CD4+ T cells, in patients with advanced cancer has also been shown to correlate with performance status, unfavorable prognostic factors, and worse survival." (PMID 33267869, 2020). "Through the analysis of naïve CD4 and CD8 T-cells (CD62LhighCD44low), the authors showed, after transplantation, the recovery of Atm-deficient mice, characterized by robust lymphopenia." (PMID 33142696, 2020). "Blood biological examination profound lymphopenia of 240/mm3 [17 CD4/mm3 (7%) and 32 CD8/mm3 (14%)]." (PMID 32228484, 2020). "Given the limitations of our cross-sectional study, and the clinical significance of lymphopenia and of CD4+ T-cell count, further longitudinal studies with serial sampling are needed to define this further." (PMID 32641700, 2020). "Meanwhile, lymphopenia and wake immune responses [e.g., lower CD3, CD4, or CD19 counts (all HR < 1)] were associated with disease deterioration and death." (PMID 32903644, 2020). "Nevertheless, prolonged CD4+ and CD8+ lymphopenia was observed in patients with SARS-CoV and associated with more severe illness and death." (PMID 32499988, 2020). "Direct attacks on CD4+ T cells, immune activation and redistribution of CD4+ T cell are contributing mechanisms in very different proportion for CD4+ T cell lymphopenia in both diseases." (PMID 33384690, 2020). "This 2 weeks timing already reported as a risk period for clinical events was characterized by the lowest HLA-DR expression on monocyte subsets associated with the deepest CD4 and CD8 T-cells lymphopenia." (PMID 33178207, 2020). "This condition is characterised by hypomagnesaemia, CD4+ lymphopenia and defective T-lymphocyte activation." (PMID 33317521, 2020). "No CD8 T-cell depletion was observed with PBS, plasma from a healthy control donor or plasma from our index patient with ALPS-FAS and CD4 lymphopenia." (PMID 31191551, 2019). "Risk factors for cryptococcosis include HIV infection, organ transplantation, use of steroid or immunosuppressive agents, malignancy, sarcoidosis, idiopathic CD4+ lymphopenia, rheumatologic diseases, and anti-GM CSF autoantibodies." (PMID 31080714, 2019). "Disseminated warts have also been frequently found in several autosomal recessive genetic defects that present with CD4 lymphopenia (e.g., RAG1, RHOH, MST1, CORO1A, DOCK8)." (PMID 31781092, 2019). "IL-2, a key cytokine responsible for both CD4+ and CD8+ T cell proliferation, has been evaluated in HIV patients with severe CD4+ lymphopenia." (PMID 30922400, 2019). "Lymphocytes undergo apoptosis even during the early stage of sepsis, and thus lymphopenia in CD4 T cells was also observed in lymphoid organs, as shown in our CLP model." (PMID 31323786, 2019). "While NK cell and CD8+ T cell or B cell lymphopenia correlate poorly with OS, CD4+ lymphopenia and severe lymphopenia (<200/mm3) strongly impact patient survival with respectively 40% and 90% reduction of the median OS or PFS." (PMID 30922400, 2019). "Our findings support a potential inverse relationship between lymphopenia, specifically CD4+ T-cell lymphopenia, and CMV disease among hospitalized SLE patients." (PMID 31574798, 2019). "While CD4 lymphopenia is mostly detected in advanced or metastatic stages, functional impairment of immune cells (NK, monocytes, memory CD4+ and CD8+ T cells) can be detected in patients with localized primary tumors (BC, colon carcinoma, HCC)." (PMID 30922400, 2019). "In the blood, significant lymphopenia was evident during early and late stage, with 10- to 20-fold reduction in B cells, CD4+ and CD8+ T cells, and NK cells." (PMID 31790513, 2019). "Biologically inhibitory anti-GM-CSF autoantibodies have been associated with cryptococcal meningitis in some otherwise immunocompetent patients and in those with idiopathic CD4+ lymphopenia." (PMID 30755511, 2019).
lymphopenia (continued). "Both patients manifested lymphopenia (affecting CD8+ more than CD4+ T cells), a restricted T cell repertoire with presence of clonotypic expansions, and markedly defective T cell proliferation in response to anti-CD3." (PMID 31440487, 2019). "The patient developed at the age of 25 years a persistent CD4+ T cell lymphocytopenia (CD4+ T cells < 200/μL) and has been since then prophylactically treated with co-trimoxazole and fluconazole." (PMID 30987377, 2019). "CD4+ lymphopenia is key in the clinical evolution of HIV patients, is common in many advanced cancer patients with pancreatic cancer, melanoma, NHL, BC, sarcomas or hepatocellular carcinoma (HCC)." (PMID 30922400, 2019). "For example, ovalbumin-specific CD4+ T cells from OT-II TCRtg mice represent one of several T cells clones, which are resistant to lymphopenia-induced activation." (PMID 30792713, 2019). "FTY720 treatment also led to lymphopenia and affected both the percentage of total lymphocytes (69.98 ± 1.182% to 44.77 ± 1.320, P < 0.001) and CD4 cells (26.40 ± 1.895% to 13.70 ± 0.6234, P < 0.001) in the spleen." (PMID 30949176, 2019). "Pronounced CD4 T-cell lymphopenia occurs in some CVID patients, and reductions in naive CD4 T cells were associated with splenomegaly, autoimmunity, and polyclonal lymphoproliferation." (PMID 31803177, 2019). "Among the here presented cases, one patient presented a significant CD4+ T cell lymphopenia, indicating a late-onset CID." (PMID 30987377, 2019). "This emphasizes the importance in future immunotherapy clinical trials to analyze the combination of CD4 lymphopenia, TCR diversity and intensity of the T cell response." (PMID 30922400, 2019). "In summary, we demonstrate that the sensitivity of CD4+ T cells to lymphopenia is not only determined by cell-intrinsic properties but also by a complex interplay between CD4+ T cells, the commensal microflora and IFN-γR+ DCs." (PMID 30792713, 2019). "Here, we provide evidence for an additional, host-dependent mechanism restraining LIP of lymphopenia-insensitive CD4+ T cells." (PMID 30792713, 2019). "At the age of 10 months, she showed moderate lymphopenia, predominantly on naïve CD4 T cells and B cells." (PMID 31273937, 2019). "A repeat evaluation at age 8 months showed progressive lymphopenia with a reduction in CD4+ naïve T cells as well as reduced T cell repertoire diversity." (PMID 31921190, 2019). "In mouse models of chemotherapy-induced lymphopenia, IL-7 accelerates CD4+ and CD8+ T cell repopulation in spleen and lymph nodes." (PMID 30922400, 2019). "Herein, we report for the first time on the paradoxical occurrence of CD4 lymphopenia in the context of ALPS-FAS, a heterogeneous genetic disorder of lymphocyte homeostasis dominated by benign lymphoproliferation and autoimmune phenomena." (PMID 31191551, 2019). "In multivariate analyses, CD4+ lymphopenia is an independent poor prognosis factor for OS in several cohorts of advanced BC (1st line and > 2nd line), and other solid tumors (NHL, myelomas and sarcomas)." (PMID 30922400, 2019). "Our results suggest, that evaluation of distinct lymphocyte subsets as CD4+ T cells allow a more detailed evaluation to weigh and interpret degree of lymphopenia and treatment response in fingolimod treated patients." (PMID 30524432, 2018). "Hematological studies showed CD4 lymphopenia with a profound dysregulation of immunoglobulin levels (decreased IgG, increased IgM and IgA)." (PMID 30386345, 2018). "Immunophenotyping of the peripheral blood mononuclear cells (PBMCs) revealed that both patients had significant T-cell lymphopenia characterized by low naïve CD4+ T-cell (CD4+CD31+CD45RA+, recent thymic emigrant cells) counts." (PMID 29725107, 2018). "Both patients presented in childhood with recurrent infections, CD4 lymphopenia and dysregulated immunoglobulin levels." (PMID 30386345, 2018).
lymphopenia (continued). "After acute LF recovery, patients overcome the initial lymphopenia and develop a strong CD4+ immune response against NP and GP2." (PMID 30373278, 2018). "Because immunoglobulin dysregulation, CD4 lymphopenia and recurring infections persisted, targeted sequencing of the PID associated activation-induced cytidine deaminase (AID) and uracil DNA glycosylase (UNG) genes was carried out, but revealed no mutations." (PMID 30386345, 2018). "We describe a series of five LIG4 deficiency patients with a wide spectrum of clinical manifestations, ranging from short stature and asymptomatic CD4+ lymphopenia, to liver failure with sudden massive bleeding." (PMID 30719430, 2018). "In contrast, fatal cases show poor inflammatory responses characterized by lymphopenia, that affects all lymphocyte subpopulations, including CD4+ and CD8+ T cells, B cells, and NK cells, along with necrosis of lymphoid organs." (PMID 30373278, 2018). "The prevalence of lymphopenia was 0%, 0%, 4.2%, 11.9%, 42.9% and 22.2% for patients with CD4 count > 500, 350-500, 200-349, 100-199, 50-99 and < 50 cells/μl, respectively, (p = 0.000)." (PMID 29632668, 2018). "Four out of five of our patients are dead from lymphoma or bone marrow failure, with severe infection and massive bleeding; the fifth patient is asymptomatic despite a persistent CD4+ lymphopenia." (PMID 30719430, 2018). "Family history was positive and investigations revealed CD4 lymphopenia, with undetectable immunoglobulins." (PMID 30305145, 2018). "As expected, we found that patients with CD4 count less than 200cells/μl presented with a significantly increased prevalence of lymphopenia." (PMID 29632668, 2018). "Patients displayed immunosuppressive phenotype, as demonstrated by a decreased mHLA-DR expression and profound CD4+ lymphopenia." (PMID 29404815, 2018). "CD4+ T cell lymphopenia and/or decrease naïve T cells is also a frequent phenotype, which can be considered as an immunological hallmark of a T-cell defect." (PMID 29942301, 2018). "Immunological characterization revealed CD4 lymphopenia, increased level of DNTs (13.2%) and hypergammaglobulinemia leading to the initial clinical diagnosis of ALPS like disease." (PMID 30386345, 2018). "Primary immunodeficiencies such as idiopathic CD4+ lymphopenia (CD4 T-cell count < 300 cells/μl) and idiopathic neutropenia (neutrophil count < 200 cells/μl) are rare disorders that have been associated with elevated risk of virus-associated cancers." (PMID 30315476, 2018). "Laboratory studies showed severe lymphopenia, decreased CD4+ and CD8+ T cell and CD19+ B cell counts, and reduced levels of all subclasses of immunoglobulins, suggesting GS." (PMID 29631544, 2018). "Nevertheless, CD4+ lymphopenia and low mHLA-DR expression were still present at ICU discharge for most patients." (PMID 28770544, 2017). "We chose Gnb2l1F/F; CD4-Cre mice because peripheral T cell lymphopenia in these mice is more profound than that in Gnb2l1F/F; lck-Cre mice." (PMID 28572806, 2017). "CD4+ lymphocytopenia with reduced numbers of naïve T cells and an accumulation of CD8+ TEMRA have also been observed." (PMID 28747912, 2017). "She presented with lymphopenia with low naïve CD4 and CD8 T cells, impaired proliferation to PHA, elevation of TCRγδ T cells, and very low B and NK cells." (PMID 28747912, 2017). "In the uremic environment, lymphopenia and the calculated absolute number of CD4 T cells lie on the left, while the activated CD4 T cells hold the position of the right." (PMID 28726529, 2017). "Apart from the neutrophil dysfunction, this patient also showed leukocytosis, CD4 lymphopenia, and reduced levels of IgA and IgM." (PMID 29430280, 2017). "Although it was termed CD4+ lymphopenia, about 40% of these patients had both low CD4+ and CD8+ cell counts, which was associated with higher risk of infections and mortality." (PMID 28770187, 2017).
lymphopenia (continued). "It is possible that peripheral T cell lymphopenia in Gnb2l1F/F; lck-Cre mice and Gnb2l1F/F; CD4-Cre mice was due to impaired autophagy." (PMID 28572806, 2017). "On day 3–4, 46% of patients presented CD4+ lymphopenia [median 515 (IQR 343–724) mm−3] versus 34% at ICU discharge [median 642 (IQR 459–846) mm−3]." (PMID 28770544, 2017). "With regard to adaptive immunity, CD4+ T lymphopenia occurring during sepsis is a major component of immunosuppression." (PMID 28770544, 2017). "Collectively, these data point to a lymphopenia predominantly affecting CD4+ T cells, and provide evidence of DC activation as an early consequence of innate immune activation." (PMID 28498840, 2017). "Eighteen patients (46%) had CD4+ lymphopenia (<500 mm−3) on day 3–4 and 10 (34%) had CD4+ lymphopenia at discharge." (PMID 28770544, 2017). "A sub-study of the CADIRIS trial Immunologic effects of maraviroc in HIV-infected patients with severe CD4 lymphopenia starting antiretroviral therapy." (PMID 28736763, 2017). "Immune dysregulation in patients with PHTS included lymphopenia, CD4+ T-cell reduction, and changes in T- and B-cell subsets." (PMID 27477328, 2017). "Examination of the T-cell repopulation kinetics after irradiation showed that rapamycin administration delayed recovery of CD8+ and CD4+ T-cell populations from the partial lymphopenia induced by low-dose irradiation." (PMID 28279220, 2017). "Along with a CD4+ T-cell lymphopenia, FOXP3+ T-cell numbers are reduced in the blood of patients with PHTS, but we observed normal frequency of Treg cells in the blood and colon." (PMID 27477328, 2017). "Lab tests identify a hypoalbuminemia, a high 24-h stool ?1-antitrypsin clearance, a hypoglobulinemia and lymphopenia (specially CD4) as consequences of the lymphatic leakage." (PMID 28491220, 2017). "Among the 15 patients with a blood sample at 6 months, only one patient presented CD4+ lymphopenia 6 months after ICU discharge." (PMID 28770544, 2017). "Particularly, CD4 lymphopenia with reversed CD4/CD8 ratio should raise the suspicion of HIV infection." (PMID 28443591, 2017). "This lymphopenia is profound, with 40% of patients having a CD4 count of <200 cells/mm3, and long-lasting, with low counts commonly persisting for over one year." (PMID 29371985, 2017). "Although immunodeficiency is a major feature of APDS, expansion of CD8 T cells is commonly observed (70%) and, together with CD4 lymphopenia, explains the inverted CD4:CD8 ratios found in the disease (71%)." (PMID 29387064, 2017). "In the present study, almost half of patients had CD4+ T lymphopenia on day 3–4 and this lymphopenia remained present for one-third of patients at ICU discharge although it was not correlated with the ICU length stay." (PMID 28770544, 2017). "Among patients with a 6-month blood sample, normal values of mHLA-DR were found for all patients [median 32,616 (IQR 24,918–38,738) AB/C] except for one and only another one presented CD4+ lymphopenia." (PMID 28770544, 2017). "Immunopathology associated with lymphoproliferative cluster 2 specifically that additionally carried over to the lymphoproliferative cluster in total included CD4+ T cell lymphopenia (<419 cell/μL), high serum IgM (>334 mg/dL), and low C3 levels (<93 mg/dL)." (PMID 29375540, 2017). "Laboratory findings often include hypogammaglobulinemia, lymphopenia, and reversed CD4/CD8 ratio; eosinophilia has also been reported in few cases." (PMID 27222657, 2016). "Specifically, infiltration of parenchymal organs with CD4+ tumor cells, inflammation, increased C-reactive protein, release of inflammatory cytokines, pleural effusion, and peripheral blood lymphopenia." (PMID 27725924, 2016). "Both patients had severe lymphopenia at each time of testing, with commitment of both lymphocyte phenotypes (CD4+ and CD8+)." (PMID 27982165, 2016).
lymphopenia (continued). "These aberrancies are even more apparent with progression to RRMM; however, significant additional immunological changes have occurred that include CD4+ T lymphopenia and increased inflammatory cytokine production." (PMID 27599546, 2016). "The patient had severe CD4 lymphopenia at 104 CD4 cells/μl (normal range 450–1,350 cells/μl) with a total lymphocyte count of 2.6 x 103 lymphocytes/μl." (PMID 27711109, 2016). "This resulted in moderate lymphopenia as reflected in a reduced number of CD4+FoxP3− Tcons in the spleen." (PMID 26973650, 2016). "This invariably resulted in profound CD4 lymphopenia and an accompanying phenotype of multiple bacterial and viral infections, and mucocutaneous candidiasis." (PMID 26801501, 2016). "Despite the lymphopenia, in the periphery, the phenotype of CD4+ T cells from Gimap5sph/sph mice is comparable to that of control mice." (PMID 27023180, 2016). "After the exclusion of HIV and malignancies (biopsy of an inguinal lymph node, bone marrow biopsy, and PET), an idiopathic CD4 lymphocytopenia was diagnosed." (PMID 26491451, 2015). "The lymphopenia and expression of CD44highCD62Llow markers by CD4+ T cells are indicative of lymphopenia-induced proliferation and resemble the CD4+ T cell phenotype first described in the adoptive transfer T cell model of colitis." (PMID 25944983, 2015). "After a thorough review of the literature, the case of N. farcinica brain abscess of the 19-year-old male was the only case of Nocardia brain abscesses reported in a patient with Idiopathic CD4+ Lymphocytopenia." (PMID 26448886, 2015). "The lymphopenia in these first two groups affected overall T and B lymphocyte subsets, as well as CD4+ and CD8+ T cell subsets." (PMID 26581890, 2015). "CD4+ T cell-specific lymphopenia in acute UCM was only significant when the subset was presented as absolute counts at both sites, and this too normalized during convalescence." (PMID 26335932, 2015). "Other weak near threshold TCR signals in CD4+ T cells leading to in vivo functional outputs in CD4+ T cells include clonal competition in the periphery in response to lymphopenia." (PMID 25539815, 2015). "This HIV-seronegative subject has a chronic idiopathic CD4+ lymphopenia leading to an extremely low CD4+/CD8+ ratio in his circulating T cells." (PMID 26552867, 2015). "One of these events was, despite the systemic T lymphopenia, an unanticipated accumulation of aberrant CD4+ T cells including regulatory T cells retaining TAK1 in mucosal tissues of LTAC mice, eventually contributing to the disease onset." (PMID 26132627, 2015). "Naïve PD-1 KO CD4 T cells gave rise to higher numbers of TEM-phenotype lymphopenia-induced proliferation memory cells." (PMID 25803808, 2015). "Lck-Cre disruption of both genes resulted in an accumulation of mature (TCRhi CD24lo) CD4 SP thymocytes and a CD4+ lymphopenia similar to those seen with Cd4-Cre disruption." (PMID 26328764, 2015). "Nocardial brain abscesses in patients with idiopathic CD4+ lymphopenia are exceedingly rare in the literature." (PMID 26448886, 2015). "CD4 T lymphocytes with a phenotype similar to MP cells can arise through lymphopenia-induced-proliferation (LIP-memory cells) and co-stimulatory molecules have been shown to interfere with this process." (PMID 25803808, 2015). "Previous studies have implicated adaptive immune system dysfunction in ALS patients and mutant SOD1 mice, showing accelerated thymus inactivation or involution, reduced CD4+ T cell number, spleen shrinkage and lymphopenia." (PMID 25889790, 2015). "For example, within our cohort, two patients with CD4 lymphopenia and either diabetes or alcohol excess developed VL relapses." (PMID 25831056, 2015). "One of the reasons that Balb/c mice were used in this study is that, lymphopenia in total CD4+ T cells and naïve CD4+ T cells in the spleen has been demonstrated in aged mice." (PMID 24586733, 2014).